TET1 (tet methylcytosine dioxygenase 1)
Diseases named in the same sentence as TET1 in open-access papers (continued):
Sharing a sentence is not in itself a finding about the gene and the disease.
lung carcinoma (25 papers, 2016 to 2025). "Genes KRT81, SPP1, PCDH7, SLC2A1, and TET1 were significantly upregulated in tumor tissues and associated with poor prognosis and survival, providing insights for exploring lung cancer biomarkers in future studies." (PMID 41415280, 2025). "Collectively, these findings highlight TET1's multifaceted role in lung cancer biology and its potential as a therapeutic and diagnostic target." (PMID 40520993, 2025). "KRT81, SPP1, PCDH7, SLC2A1, and TET1 are associated with poor prognosis and survival outcomes, providing novel insights for exploring lung cancer biomarkers." (PMID 41415280, 2025). "Ectopic expression of TET1 effectively inhibits the growth of the lung cancer, while knockdown of TET1 causes lung adenocarcinoma cells to develop resistance to EGFR inhibitors." (PMID 34656178, 2021). "Three genes (TET1, ARID1B, and BAZ1A) are highly mutated in breast and lung cancer types, whereas TET1, IDH2, and ARID1B were also among the top genes altered in several cancer types, further corroborating their putative role as cancer drivers." (PMID 32963031, 2020). "Loss of TET1 expression or mislocalized cytoplasmic TET1 is detectable in a substantial percentage of patient-derived lung cancer samples (~44%), suggesting that TET1 is likely inhibited in lung cancer." (PMID 35269796, 2022). "In most lung cancer cases, TET1 expression is either reduced or predominantly localized in the cytoplasm, limiting its tumor-suppressive potential." (PMID 40520993, 2025). "The functional importance of TET1 in lung cancer has been further emphasized in studies exploring its interactions and regulatory networks." (PMID 40520993, 2025). "Yokoyama et al57 demonstrated that TET1-driven DNA hypomethylation regulated mucin 4 (MUC4) expression in lung cancer, with reduced TET1 levels leading to decreased MUC4 levels." (PMID 40520993, 2025). "In lung cancer, oncogenic epidermal growth factor receptor‐mediated signals inhibit the expression of tumor‐suppressive genes through TET1 inhibition." (PMID 36345848, 2023). "Although driver mutations of TETs are infrequent in lung cancer, with TET2 having a higher frequency of somatic mutations compared to TET1 and TET3, an altered expression of TETs has been observed." (PMID 35205708, 2022). "-Oncogenic EGFR was shown to silence multiple tumor suppressors in lung cancer cell lines via transcriptional downregulation of TET1 by the C/EBPα transcription factor." (PMID 35269796, 2022). "Altogether, these results indicate that the disruption of TET1 function can lead to the demethylation-dependent inactivation of tumor suppressor genes in lung cancer as well as adversely affect patients’ response to therapeutic options." (PMID 35269796, 2022). "Both in vitro and in vivo experiments showed that TET1 overexpression inhibited lung cancer cell proliferation, migration and invasion, while knockdown of TET1 resulted in the opposite effect." (PMID 34656178, 2021). "Epidermal growth factor receptor (EGFR) and MAPK activation-mediated silencing of TET1 was observed in cellular and animal models of lung cancer, but the validity of such a mechanism in human lung cancers is uncertain." (PMID 31842975, 2019). "Another functional experiment displays that aberrant activation of miR-767 devotes to tumor epigenesis in lung cancer via repressing TET1/3 mRNA and regulating genomic 5-methylcytosines to 5-hydroxymethylcytosines levels." (PMID 31601173, 2019).
lung carcinoma (continued). "This is the first report that TET1 mediated DNA hypomethylation regulates the expression of MUC4 in lung cancer." (PMID 28680536, 2017). "We showed a significant reduction of MUC4 mRNA by TET1 mRNA down-regulation in a lung cancer cell line." (PMID 28680536, 2017). "Homozygous deletions of SMARCB1 are found only in brain cancers, while homozygous deletions of TET1 were almost exclusively observed in lung cancer (seven out of eight cases)." (PMID 29089486, 2017). "Early stage lung cancers showed higher expression of TET1 and Dnmt3a than other advanced stages (p=0.011 and p=0.014 respectively)." (PMID 28680536, 2017). "Another example was miR-29 that directly targeted TET1 in lung cancer cells, and all TET family members in human dermal fibroblasts and vascular smooth muscle cells." (PMID 27141829, 2016). "The role of TET1 in lung cancer continues to be an area of active research and debate." (PMID 40520993, 2025). "In the lung cancer cell line H1299, TET1 is required for the expression of mesenchymal genes N-cadherin and vimentin as well as for the expression of INSIG1, a master regulator of cholesterol biosynthesis that drives hypoxia-induced EMT in a catalytic-site independent manner." (PMID 40764968, 2025). "In addition, small/short hairpin RNAs (shRNAs)-induced TET1 knockdown confers resistance to EGFR inhibitors in lung cancer cells." (PMID 35269796, 2022). "However, the expression changes in TETs, especially for TET2 and TET3, in lung cancer remain somewhat unclear, with conflicting observations for TET1 in cell lines and primary tumor models." (PMID 35205708, 2022). "Usually, TET1 in lung cancer showed decreased expression or cytoplasmic localization." (PMID 34656178, 2021). "Although the oncogenic role of TET1 inhibition against EGFR has been established in cellular and animal models of lung cancer, its role in patient prognosis is still inconclusive and worth further investigation." (PMID 34656178, 2021). "Mining gene expression data of lung cancer cell lines identified additional TSGs suppressed by KRAS signaling whose expression was restored by inhibition of miR-29b and re-expression of TET1." (PMID 29088821, 2017). "Notably, TET1 was identified, a gene reported as an EGFR-TKI-induced factor in lung cancers and glioblastomas, supporting the reliability of our approach." (PMID 40290805, 2025).
melanoma (21 papers, 2015 to 2024). A malignant, usually aggressive tumor composed of atypical, neoplastic melanocytes. "As our study also supports TET1 mutation as a potential predictive biomarker, particularly for colorectal and melanoma patients, this warrants continued clinical investigation." (PMID 35798829, 2022). "As TET1 mutations were most common in colorectal cancer, bladder cancer, and melanoma patients, we subsequently evaluated the relationship between TET1 mutation and overall survival in these cancers specifically." (PMID 35798829, 2022). "In seminomas, PRAME expression correlated with TET1, but in melanomas and synovial sarcomas, it correlated with both DNMTs and DNMT3A, respectively." (PMID 38541782, 2024). "A previous study has demonstrated the association of TET1 mutations with high responses to ICIs in NSCLC, bladder cancer, head and neck squamous cell carcinoma (HNSCC), melanoma, and esophagogastric cancer." (PMID 35395805, 2022). "One study showed that IDH2 and TET1 expression was reduced in melanoma compared with that in melanocytic naevi." (PMID 33024276, 2020). "Therefore, we analyzed expression of TET1, -2, and -3 in B16 melanoma and CT-26 tumors and found that TET2 was expressed at the highest level, with TET3 at intermediate levels and TET1 at the lowest level." (PMID 39388288, 2024). "Indeed, the overexpression of TET2 in melanoma cells suppresses tumor initiation and progression by increasing 5hmC levels, and elevated 5hmC by upregulated TET1 recruits the CHOIP-methylosome complex near the genes involved in glioblastomagenesis." (PMID 33926529, 2021). "As TET1 and PTPRD mutations were the only significant predictors of outcomes in the melanoma discovery cohort, we next explored their prognostic utility in a valuation cohort consisting of melanoma patients from three independent immunogenomic studies all receiving ICIs (N = 212)." (PMID 35798829, 2022). "Though TET1 mutations were observed across a wide range of different cancers, TET1 mutations were most strongly associated with improved responses to ICI-based immunotherapy in colorectal and melanoma patients, and in the case of colorectal cancer, exceeded the predictive value of TMB." (PMID 35798829, 2022). "Specifically, TET-1 could be proposed in the case of cutaneous diseases affecting more superficial strata, such as acute inflammatory dermatoses, and ET could be proposed to treat deeper and more serious conditions, such as basal cell carcinoma and melanoma." (PMID 36499432, 2022). "The expression of TET enzymes, particularly of the three members TET1, TET2, and TET3, can vary between melanocytes and melanoma in different stages." (PMID 37834158, 2023). "In contrast to DNMTs, the ten eleven translocation (TET) family of DNA demethylases (TET1, TET2, and TET3) are commonly downregulated in melanoma, and melanoma cells accordingly show reduced levels of 5hmC in their DNA compared with melanocytic nevi." (PMID 33024276, 2020). "We first evaluated the expression level of TETs (TET1, TET2, and TET3) in primary cultured healthy human melanocyte lines (FOM-113) and various melanoma cell lines using qRT-PCR." (PMID 25977731, 2015). "Of the cell lines evaluated, the lowest expression level of both TET1 and TET2 was observed in two metastatic melanoma cell lines." (PMID 25977731, 2015). "Consistent with a previous report, we found that the expression of TET1 and TET2 was consistently decreased in all melanoma cell lines examined, as compared to the normal melanocyte line." (PMID 25977731, 2015). "TET1 immunopositivity was present in 90% (71/79) of seminomas, and 2% (2/102) of synovial sarcomas had faint immunoreactivity and all melanomas were negative." (PMID 38541782, 2024). "Consistent with our above results, TET2/3, but not TET1, were downregulated in melanoma patients in multiple GEO datasets, and TET3 expression was positively correlated with STAT3 expression." (PMID 36854755, 2023).
melanoma (continued). "Some of them such as TET1 and TET3 showed alteration in over 13%-10% of melanoma samples." (PMID 31217906, 2019). "In melanoma MeWo cells, successful re-expression by overexpression and VP160-dCas9 was observed, but no re-expression using TET1-dCas9." (PMID 38397165, 2024). "In contrast, the inferred level of expression of TET1 was lower than TET2 and TET3 and did not change between melanoma and normal skin, suggesting a less important role in regulating global 5hmC levels." (PMID 39091741, 2024). "In the melanoma cells, possibly due to the moderate methylation of RIPK3, TET1-dCas9 did not induce its epigenetic reactivation." (PMID 38397165, 2024).
colorectal cancer (20 papers, 2014 to 2025). A primary or metastatic malignant neoplasm that affects the colon or rectum. "A similar study by Cheng et al74 examined tumor samples from colorectal cancer patients and found an association between reduced TET1 levels, down-regulated by miR-21-5p, and the progression of colorectal cancer to more advanced stages." (PMID 40520993, 2025). "In one study, researchers observed a significant reduction in TET1 expression in colorectal cancer tissues compared with normal tissues." (PMID 40520993, 2025). "Findings suggest that TET1 plays a complex role in the development of colorectal cancer, influencing various aspects of tumor progression." (PMID 40520993, 2025). "Further analysis revealed that miR-21 promoted colorectal cancer cell proliferation by targeting and down-regulating TET1." (PMID 40520993, 2025). "Aberrant DNA methylation, a hallmark of colorectal cancer development, was found to affect ZNF334, with TET1 identified as a key regulator of this process." (PMID 40520993, 2025). "They discovered that miR-21, a gene regulator, was up-regulated in colorectal cancer tissues, while TET1, known to inhibit cell growth, was down-regulated." (PMID 40520993, 2025). "Deregulation of ten-eleven Translocation protein 1 (TET1) is commonly reported to induce imbalances in gene expression and subsequently to colorectal cancer development (CRC)." (PMID 38583183, 2024). "Overall, our findings shed light on the intricate interactions between TET1, Wnt1, and specific miRNAs in colorectal cancer (CRC) and their potential implications for diagnosis and treatment." (PMID 39495308, 2024). "Alterations in TDG expression are a biomarker for melanoma and colorectal cancers (CRCs) and play a role with TET1 in genomic instability through DNA demethylation and inflammation." (PMID 38914477, 2024). "We demonstrated that TET1 is concentrated in coarse nuclear bodies (NB) and 5-hydroxymethylcytosine (5hmC) in foci in colorectal cancer cells (HCT116, Caco-2, and HT-29)." (PMID 38583183, 2024). "miR‐21 was found to be underexpressed in cytogenetically normal AML with high Tet methylecytosine deoxygenase 1 (TET1), while some studies have found miR‐21 to target TET1 in colorectal cancer." (PMID 36051053, 2022). "Although the mechanism is different, it is consistent with the previous study in colorectal cancer cells; TET1 also inhibits the Wnt pathway indirectly by promoting the expression of Wnt suppressors DKK3 and DKK4 to, therefore, prohibit cell proliferation." (PMID 35805009, 2022). "No detectable TET1 protein was observed in the CRC cell lines with low TET1 mRNA level, indicating that the decreased TET1 mRNA level resulted in low TET1 protein level in colorectal cancer." (PMID 26816554, 2016). "Consistent with the finding of F Neri and another previous report, only TET1 was significantly decreased in the colorectal cancer tissues and cell lines at mRNA level." (PMID 26816554, 2016). "In addition to TET1 and RNF43, our study also identified an association between NCOA3, CREBBP, and NOTCH3 mutations and improved survival in colorectal cancer patients." (PMID 35798829, 2022). "In a previous study, 5hmC was shown to be positively correlated with depth of tumor invasion in colorectal cancer, and depletion of TET1, which could oxidize 5mC to 5hmC, could facilitate cell invasion." (PMID 33203436, 2020). "TET1 methylation is connected with CpG island methylator phenotype (CIMP) in colorectal cancer." (PMID 28241740, 2017). "Thus, TET2 could also be a tumor suppressor in colorectal cancer, and the tumor suppressor function of both TET1 and TET2 was impaired in colorectal cancer through different mechanism." (PMID 26816554, 2016). "The ten-eleven translocation 1 (TET1), which is essential for active DNA demethylation, plays a multifaceted role in the pathogenesis of colorectal cancer." (PMID 35395805, 2022).
colorectal cancer (continued). "Bioinformatics analyses reveal prevalent hypermethylation of TFPI2 was an early event in tumorigenesis of colorectal caner, and expression of TET1 and TFPI2 was positive correlation in colorectal cancer and normal tissue." (PMID 30651599, 2019). "Expression of TET1 in individuals with IBD turned out to be significantly higher than in the controls (p = 0.0002), persons with polyps (p = 0.0164) and colorectal cancer patients (p = 0.0064)." (PMID 30029654, 2018). "Finally, moderate inverse correlations were found between TET1 expression and 5-hmdU level (r = − 0.4236, p = 0.035) in persons with polyps, and between TET2 expression and 5-cadC level (r = − 0.5324, p = 0.023) in colorectal cancer patients." (PMID 30029654, 2018). "TET1/FOXO4: Reduced expression levels of TET1 and FOXO4 have been identified as a prognostic indicator for colorectal cancer, indicating a negative correlation with patient outcomes." (PMID 40951343, 2025). "Decreased ten-eleven translocation 1 (TET1) messenger RNA (mRNA), but not other two TET family members, has been observed in the colorectal cancer and is crucial for colorectal cancer initiation." (PMID 26816554, 2016).